SSH2 (slingshot protein phosphatase 2)
Description:
Protein phosphatase which regulates actin filament dynamics. Dephosphorylates and activates the actin binding/depolymerizing factor cofilin, which subsequently binds to actin filaments and stimulates their disassembly. Inhibitory phosphorylation of cofilin is mediated by LIMK1, which may also be dephosphorylated and inactivated by this protein. Required for spermatogenesis (By similarity). Involved in acrosome biogenesis, probably by regulating cofilin-mediated actin cytoskeleton remodeling during proacrosomal vesicle fusion and/or Golgi to perinuclear vesicle trafficking (By similarity).
Synonyms: SSH-2L; KIAA1725; SSH-2
Tractability: PROTAC: ubiquitination databases record sites on it; its protein half-life has been measured.
Target class: Phosphatase; Protein Phosphatase; Enzyme
Gene: Protein-coding gene on chromosome 17 (29,625,938 to 29,930,276, reverse strand). Ensembl gene ENSG00000141298.
Subcellular location: Cytoplasm; Cytoplasm, cytoskeleton; Cell junction, focal adhesion; Cytoplasmic vesicle, secretory vesicle, acrosome
Gene Ontology:
Molecular function: actin binding; phosphoprotein phosphatase activity; protein binding; phosphatase activity; protein serine/threonine phosphatase activity; protein tyrosine phosphatase activity
Biological process: actin cytoskeleton organization; protein dephosphorylation; negative regulation of actin filament polymerization
Cellular component: extracellular region; cytoplasm; acrosomal vesicle; cytoskeleton; focal adhesion
Genetic constraint (gnomAD): Loss-of-function variants: 34 observed, 120.93 expected, observed/expected ratio (o/e) 0.28, 90% interval 0.21 to 0.37. The upper end of that interval is the gene's LOEUF score, 0.37, which puts it in group 1 of 6, group 1 being the genes least tolerant of losing a copy. Missense variants: 1,360 observed, 1,765.4 expected, observed/expected ratio (o/e) 0.77, 90% interval 0.74 to 0.81. Synonymous variants: 602 observed, 652.83 expected, observed/expected ratio (o/e) 0.92, 90% interval 0.86 to 0.99.
Homologues: Orthologues: chimpanzee SSH2 (99% identical), macaque SSH2 (97% identical), rabbit SSH2 (88% identical), guinea pig SSH2 (86% identical), dog SSH2 (86% identical), pig SSH2 (83% identical), rat Ssh2 (82% identical), mouse Ssh2 (82% identical), tropical clawed frog ssh2 (57% identical), zebrafish ssh2a (37% identical), zebrafish ssh2b (34% identical). Paralogues in human: SSH1 (30% identical), SSH3 (17% identical), STYXL2 (10% identical), DUSP16 (9% identical), DUSP8 (8% identical), DUSP7 (7% identical), DUSP6 (7% identical), DUSP4 (6% identical), DUSP1 (6% identical), DUSP9 (6% identical), DUSP5 (6% identical), DUSP10 (6% identical), and 19 more.
Diseases named in the same sentence as SSH2 in open-access papers:
SSH2 is named in the same sentence as 14 diseases in open-access papers, as found by Europe PMC text mining. Sharing a sentence is not in itself a finding about the gene and the disease. The quoted sentences say what the papers report.
Alzheimer disease (1 paper, 2024). A progressive, neurodegenerative disease characterized by loss of function and death of nerve cells in several areas of the brain leading to loss of cognitive function such as memory and language. "In contrast, the gene EPB41L2 (1.079, 1.029 − 1.130, P = .001), MYO1F (1.083, 1.004 − 1.168, P = .039), and SSH2 (1.049, 1.015 − 1.083, P = .004) were associated with a higher risk of developing Alzheimer’s disease." (PMID 39560568, 2024).
Azoospermia (1 paper, 2023). Absence of any measurable level of sperm,whereby spermatozoa cannot be observed even after centrifugation of the semen pellet. "The abnormal phenotype Ssh2 KO in the mouse model may be valuable to understand the pathological factors causing azoospermia in humans." (PMID 36942942, 2023). "The Slingshot family is evolutionarily conserved in mammals, therefore we believe that some mutations in the SSH2 gene should exist in non-obstructive azoospermia, although no report was published yet that highlighting such mutation." (PMID 36942942, 2023).
colon cancer (1 paper, 2021). "SSH2 was recently reported to drive proliferation in colon cancer stem cells." (PMID 34165249, 2021).
epilepsy (1 paper, 2025). A brain disorder characterized by episodes of abnormally increased neuronal discharge resulting in transient episodes of sensory or motor neurological dysfunction, or psychic dysfunction. "We found that CDC25B, DNMT1, GZMA, MTX1, and SSH2 expression decreases epilepsy risk, whereas FGD3, RAF1, and SH3BP5L increase it." (PMID 39753851, 2025). "In our study, both FGD3 and SSH2 were significantly upregulated at the transcriptomic and proteomic levels in epilepsy." (PMID 39753851, 2025).
infertile (1 paper, 2023). "The data indicated infertile status as no pups were obtained when adult Ssh2 KO males were mated with WT fertile females (8 weeks of age)." (PMID 36942942, 2023).
male infertility (1 paper, 2023). The inability of the male to effect fertilization of an ovum after a specified period of unprotected intercourse. "Ssh2 knockout (KO) causes severe reproductive defects and male infertility in mice." (PMID 36942942, 2023). "Our findings demonstrate that the reproductive phenotype of severe spermatogenic arrest at the early round spermatid stage with enhanced germ cell apoptosis leads to subsequent male infertility in Ssh2 KO mice." (PMID 36942942, 2023).
renal cell carcinoma (1 paper, 2023). "Elevated COFILIN phosphorylation after SSH2 knockdown was previously demonstrated to induce the activation of Caspase-3/7 in a human renal cell carcinoma cell line, and activation of Caspase-3/7 is known to trigger apoptotic cell death." (PMID 36942942, 2023).
tumor (2 papers, 2022 to 2023). "SSH2 is involved in the effective migration and invasion of tumor cells." (PMID 36672855, 2022).
cancer (1 paper, 2019). A tumor composed of atypical neoplastic, often pleomorphic cells that invade other tissues. "In addition, we identified three heterozygous candidate missense variants in known cancer susceptibility genes (BMPR1A,BRIP1, and SRC), three truncating variants in possibly novel cancer genes (CLSPN,SEC24B, SSH2) and four candidate missense variants in ACACA, NR2C2, INPP4A, and DIDO1." (PMID 30809968, 2019). "To date, no studies have implicated RBM27, SEC24B, or SSH2 in CRC or cancer development." (PMID 30809968, 2019).
infection (1 paper, 2021). The state of being infected such as from the introduction of a foreign agent such as serum, vaccine, antigenic substance or organism. "For instance, the proteins FMNL3, EPB41L1, SSH2, CORO1B and ARPC2 are detected only in E. ruminantium-infected cells, while in FSCN1 and GC, proteins are under-expressed or inhibited by infection." (PMID 34073568, 2021).
SSH2 also shares sentences with these, for which no sentence is quoted: atherosclerosis (1 paper); dementia (1); neurodegenerative disease (1); osteosarcoma (1).